IL10 (interleukin 10)
Diseases named in the same sentence as IL10 in open-access papers (continued):
Sharing a sentence is not in itself a finding about the gene and the disease.
preeclampsia (continued). "In addition, the TTR aggregates eluted from preeclampsia sera induced preeclampsia-like features, hypertension, and proteinuria in interleukin (IL)-10 knockout mice." (PMID 33670947, 2021). "As preeclampsia is deemed a more proinflammatory environment, IL-10 concentrations may be raised in response to the inflammatory environment." (PMID 33680514, 2021). "IL-10 plays a crucial role in the physiopathology of preeclampsia as an immunomodulator." (PMID 32063926, 2020). "However, levels of TNF alpha, IL-6, IL-8 and IL-10 in premature infants were found to be unaffected by the mother’s preeclampsia condition." (PMID 32063926, 2020). "It has been recently demonstrated that berberine hydrochloride could alleviate preeclampsia by regulating IL2/IL10 and BCL2/BAX expressions in preeclampsia rat models." (PMID 29765977, 2018). "Thus, even a moderate form of preeclampsia shows directional change, i.e., elevated levels of pro- and anti-inflammatory cytokines, with the exception of IL-10, while a downward trend is recorded in severe preeclampsia." (PMID 27335593, 2016). "The findings of significantly lower serum IL10 concentrations in patients with severe preeclampsia in comparison with respective concentrations in patients with moderate preeclampsia can be considered as major pathognomonic laboratory sign of severe preeclampsia." (PMID 27335593, 2016). "Low placental IL-10 levels have been associated with fetal loss, premature delivery, and preeclampsia, irrespective of the prevalence of maternal diabetes." (PMID 27294162, 2016). "Although IL-10 -1082A/G polymorphism had no obvious association with preeclampsia in the overall meta-analysis, it showed association with preeclampsia among Asian and South American populations." (PMID 25257050, 2014). "However, our findings were consistent with the latest meta-analysis result of the association between IL-10 expression level and preeclampsia, which also indicated the elevated IL-10 levels in women with preeclampsia." (PMID 25257050, 2014). "By reviewing the titles and abstracts, 355 of them were excluded because of no relevance to the association of IL-10 polymorphisms with preeclampsia." (PMID 25257050, 2014). "The results obtained reflect the phasic nature of the anti-inflammatory response: compensatory enhancement of IL-10 production in gestational hypertension and its depletion in preeclampsia, which confirms the role of monocyte-regulatory immunity in the pathogenesis of preeclampsia." (PMID 41463130, 2025). "This suggests that IL-10 may play a protective role for the fetus in cases of preeclampsia." (PMID 37168313, 2023). "Lower second trimester IL-10 concentrations may be an early predictor for developing preeclampsia." (PMID 33680514, 2021). "In addition, since development of preeclampsia was reported to be caused by defective trophoblastic invasion, probably through increased pro-inflammatory cytokine TNF-α and decreased IL-10, and VD was also reported to act as an immune modulator by downregulating TNF-α and upregulating IL-10." (PMID 29225576, 2017). "Besides, there is still a lack of meta-analysis of other IL-10 polymorphic sites' association with preeclampsia." (PMID 25257050, 2014). "However, continuous exposure to hypoxia in the early stage of pregnancy has been shown to induce preeclampsia-like symptoms in IL-10 knockout mice, suggesting that severe hypoxia itself could cause preeclampsia." (PMID 24098539, 2013). "Meanwhile, IL10 stimulates trophoblasts to generate more CCL24, maintaining the dominance of M2 macrophages in preeclampsia placental environment." (PMID 39865240, 2025). "Future investigations should aim to delineate the relationship between IL-10 and the co-occurrence of HIV and preeclampsia, with the objective of uncovering novel therapeutic avenues." (PMID 39273381, 2024).
preeclampsia (continued). "Decreased levels of anti-inflammatory cytokines (IL-10, IL-4) and increased pro-inflammatory cytokines (TNF-α, IL-6) in the circulation and placental tissue support the inflammatory background of preeclampsia." (PMID 35004644, 2021). "However, our meta-analysis results based upon four previously published relevant studies did not support the association between IL-10 -1082A/G polymorphism and the risk of preeclampsia among white women under the allelic model (G allele versus A allele, OR = 0.83, 95% CI = 0.56–1.21, P = 0.32)." (PMID 25257050, 2014). "The secondary aim was to investigate whether L. rhamnosus GG affects lymphocyte subpopulations and IL‐10 and IL‐12 levels, as well as to analyze whether a history of spontaneous PTD or preeclampsia modifies the impact on the inflammatory response." (PMID 41369322, 2025). "Preeclampsia is characterized by chronic inflammation and endothelial damage attributed to impaired IL-10 signal transduction, thus interrupting the JAK-STAT pathway resulting in downstream IL-10 downregulation." (PMID 39273381, 2024). "Preeclampsia is a state of chronic inflammation with an immune imbalance where proinflammatory cytokines are increased (TNF-α, IL-6, IL-17) and anti-inflammatory cytokines are reduced (IL-10, IL-4)." (PMID 37887854, 2023). "Individual levels of IL-10 in preeclampsia and normotensive patients were not significantly different in certain human research." (PMID 37168313, 2023). "In contrast, pro-inflammatory IL-6 and anti-inflammatory IL-10 levels were higher in preeclampsia patients compared to normal pregnancies." (PMID 37168313, 2023). "In the third trimester, most studies reported no significant change in maternal serum IL-10 concentrations between women with preeclampsia and healthy pregnancy." (PMID 33680514, 2021). "Moreover, stimulation of maternal PBMCs from women with recurrent PTB, PPROM, preeclampsia, or IUGR resulted in lower levels of IL-10 compared to gestational age-matched, healthy pregnant women." (PMID 32265904, 2020). "Levels of TNF-α, IL-1β, and IL-6 were increased but IL-10 was decreased in culture medium of monocytes from women with preeclampsia compared with those from nonpregnant and normotensive pregnant women (all p < 0.01)." (PMID 31138166, 2019). "Moreover, women with preeclampsia had significantly lower levels of IFN-gamma and IL-4 and significantly higher levels of IL-10 7 days later in comparison with the presenting levels." (PMID 28747200, 2017). "Statistical analysis showed not significant differences in serum levels of IL10 between pregnant women with preeclampsia and healthy pregnant women (p = 0.5)." (PMID 27335593, 2016). "At the same time, in placental tissue in patients with preeclampsia, on the contrary, a significant decrease in regulatory cells CD4+, CD8+, CD14+, CD56+, CD59+, activation markers CD95+, as well as anti-inflammatory cytokine IL-10, growth factors VEGFR and IGF was detected." (PMID 40647643, 2025). "In the preeclampsia group, the statistically most significant differences were found for the following markers in peripheral blood: increased levels of CD16+, CD56+, HLA-DR+, CD95+, and intracellular production of cytokines—IL-10, TNF, Perforin, GM-CSF, IGF, while reducing CD14+ levels." (PMID 40647643, 2025). "At the same time, in placental tissue in patients with preeclampsia, on the contrary, a significant decrease of regulatory cells CD4+, CD8+, CD14+, CD56+, CD59+, activation markers CD95+, as well as anti-inflammatory cytokine IL-10, growth factors VEGFR and IGF was detected." (PMID 40647643, 2025). "Moreover, the decreased level of IL-10 was present in all forms of preeclampsia regardless of its onset and severity." (PMID 34681861, 2021). "As IL-10 is a key cytokine in the regulation of inflammation, lower IL-10 concentrations in women with preeclampsia may suggest that IL-10 is not effectively controlling the proinflammatory environment that occurs during preeclampsia." (PMID 33680514, 2021).
preeclampsia (continued). "This suggests that IL-10 levels may not be a suitable marker for early detection of preeclampsia, but increasing IL-10 may be a potential therapeutic target of preeclampsia, which could lead to future studies." (PMID 34681861, 2021). "LPS stimulation may be different from the inflammatory state in preeclampsia as IL-10 was upregulated by LPS while was downregulated in preeclampsia, which might be why LPS-induced IL-10 was not enhanced in preeclampsia." (PMID 31138166, 2019). "Critically, an isolated reduction in anti-inflammatory status is not detrimental, but studies of the IL-10 knockout mouse demonstrate increased susceptibility to inflammatory stimuli resulting in PTB and fetal loss, and exacerbation of the vascular symptoms of preeclampsia and effects of hypoxia." (PMID 34670515, 2021). "Previous reports indicate that the role of vitamin D in regulating immune function is similar to that of IL-10, and vitamin D could act as an immunomodulatory agent in preparation for in vitro fertilization pre-embryo transfer or for prevention or treatment of RSA, preeclampsia or eclampsia." (PMID 28902929, 2017).
eosinophilia (74 papers, 2004 to 2025). "When the authors blocked IL-10 action in the infected group, via monoclonal antibodies, the mice became susceptible to the hyperresponsiveness, with higher eosinophilia and higher IL-5 production." (PMID 27635405, 2016). "For instance, TLR3 signaling regulates eosinophilia-associated cytokine production in CRSwNP via IL-10 production." (PMID 27584662, 2016). "In onchocerciasis, the presence of IL-10 is clearly associated with a protective immunological scenario: high IgG4, IL-10 and Treg are associated with low pathology whereas high levels of IgE, IL-4 and eosinophilia are common in patients with severe pathology." (PMID 22509424, 2012). "However, the fact that notably IL-10 is a chemoattractant suggests that eosinophilia might develop in association with PT." (PMID 25562019, 2014). "IL-10 is described as an inhibitor of eosinophilia by suppressing the production of IL-5 and GM-CSF, indirectly influencing the apoptosis and proliferation of eosinophils." (PMID 41574188, 2025). "It should be noted, however, that IL-10 suppresses hyper-responsiveness and eosinophilia in the airways mainly by inhibiting the antigen-induced recruitment of inflammatory cells." (PMID 40432071, 2025). "In another murine model study, HDM triggered more eosinophilia, higher concentrations of IL-4, IL-10, and IFN-γ in BALF compared to OVA, and the author concluded that murine models triggered by HDM were more relevant to human allergic asthma." (PMID 38302925, 2024). "IL-10-producing Treg cells inhibit Th2 responses, such as IgE conversion, eosinophilia and antihyaluronidase reaction response to antigen, thereby inhibiting the inflammatory response and reducing airway epithelial shedding." (PMID 36691058, 2023). "Blood eosinophilia was positively correlated with the serum concentrations of periostin (r = 0.35, p < 0.05), IL-6 (r = 0.49, p < 0.05), IL-10 (r = 0.66, p < 0.05), IL-12p70 (r = 0.39, p < 0.05), and ADAM33 (r = 0.59, p < 0.05)." (PMID 36835202, 2023). "IL-10 leading to eosinophil mobilization, intestinal mast cell accumulation and production of IgE, mucosal mast cell infiltration, intestinal eosinophilia, elevated serum IgE, increased level of parasite specific IgG-1 which are responsible to eradicate worms." (PMID 34335567, 2021). "At later stages, Th1/Th2 responses become more balanced, while in chronic condition Th2 response with eosinophilia and increased concentration of IgG4 and Il-10 dominates." (PMID 35145508, 2021). "The activity of these cytokines translates into specific pathophysiological phenomena such as fibrosis (TGF-β), activation of B cells and plasma cells to IgG4 production (IL-10, IL-4, IL-5), and eosinophilia (Il-5, Il-4, Il-13)." (PMID 35145508, 2021). "Smteg administration reduces eosinophilia, Th2 cytokines and allergen specific-IgE, and these effects can be mediated by a high level of IL-10 secreted by alveolar M2 macrophages and DCs." (PMID 34413850, 2021). "CD4+FoxP3+ Tregs can reduce eosinophilia, impair humoral responses and secret an inhibitory cytokines, such as IL-10 and TGFβ, which suppress the effector functions of activated T cells and reduce inflammation." (PMID 33101290, 2020). "Herein, co-administration of 10 ng VitD3 with suboptimal OVA-SCIT enhanced suppression of AHR and eosinophilia, and increased levels of IL10 and TGF-β." (PMID 33257771, 2020). "IL-10, also, decreases eosinophilia by suppressing their survival or by reducing IFN-γ production; which ameliorates eosinophilic recruitment, and by suppressing Th2 cytokines." (PMID 32024540, 2020). "In studies of the immunomodulatory function of ESPs, helminths have been shown produce ESPs to induce the generation of Th2 cytokine (IL-4, IL-10, and IL-13) by the host, inflammation, and the elevation of IgE and eosinophilia levels in the serum." (PMID 32479527, 2020).
eosinophilia (continued). "Since then, a number of studies have been conducted to demonstrate that Treg cells producing IL-10 have the ability to inhibit Th2 responses, such as IgE switching, eosinophilia, and AHR, to the antigen." (PMID 31231389, 2019). "We observed a reduction of 84% in blood eosinophilia and a decrease in the IL-4 and IL-10 blood levels after treatment." (PMID 27378927, 2016). "On the contrary, the VD3 adjuvated allergoid vaccine induced the most prominent reduction of airway eosinophilia and Th2 cytokines and concomitant increase of T regulatory cells and IL-10 in the lung and Der p 2-specific IgG2a in the serum." (PMID 27499704, 2016). "Those strains able to limit egg production and curtail infection display a suite of enhanced Type 2 responses, including in particular T cell production of IL-4 and IL-10, eosinophilia and alternatively activated macrophages." (PMID 24492801, 2014). "Dietary vitamin D deficiency in an adult model of ovalbumin-induced AAD demonstrated worse AHR, eosinophilia and reduced IL-10 levels." (PMID 24943330, 2014). "The proximity of PGE2 in the SUS plot to eosinophils and IL-10 potentially suggests ongoing suppression of eosinophilia, which would be expected at 24 h post-allergen exposure." (PMID 22438998, 2012). "IL-10 mediated suppression of allergen-induced airway eosinophilia was observed in mice infected with N. brasiliensis 4 or 8 weeks before OVA-airway challenge." (PMID 22558152, 2012). "In our studies, blockade of IL-10 in conjunction with PZQ treatment led to an increase in eosinophilia and adult worm-specific IL-4, IL-5, IFNγ and IL-17A." (PMID 21829367, 2011). "Food allergenicity is characterized by abnormal IgE production, peripheral eosinophilia, mast cell activation, and induction of Th2 lymphocytes expressing cytokines such as IL-4 and IL-10." (PMID 22091390, 2011). "The decreased eosinophilia was likely the result of increased IL-10 in the lung homogenate of the tolerized mice (6320 ± 354 ng/mL vs 5190 ± 404 ng/mL, p = 0.02)." (PMID 21092270, 2010). "The immune response in clinically asymptomatic individuals is dominated by IL-4, IL-5, IL-10, and IL-13 secretion, IgE and IgG4 antibodies, and peripheral eosinophilia." (PMID 19381284, 2009). "Alternatively, IL-10 or TGFβ support Th2 responses that impact on antibody production, mast cell degranulation and eosinophilia via secretion of IL-4, IL-5, IL-10, IL-13." (PMID 17430585, 2007). "Administration of IL-10 gene plasmids (p = 0.009) had a more significant decrease in the level of eosinophilia than those given TGF-β (p = 0.04) and IL-12 (p = 0.12) encoding vector." (PMID 16677403, 2006). "As suggested by the effect of IL-10 on airway eosinophilia, IL-10 appears to play a role in regulating eosinophils recruitment." (PMID 16677403, 2006). "Interestingly, some of these demonstrated that IL-10 can promote the development of airway hyperresponsiveness, mucus metaplasia, IL-5 production, eosinophilia, dendritic cell polarization and a Th2-skewed phenotype in allergic mice." (PMID 39935481, 2025). "A potential link between IL-10 and eosinophilia may be supported by data from IL-10−/− mice showing diminished skin infiltration of eosinophils and IL-4 and IL-5 mRNA expression in a mouse model of allergic dermatitis." (PMID 39076967, 2024). "Consequently, serum IL-10 was the only cytokine differing between the cases selected by blood eosinophilia and was higher among those at or exceeding the cut-off value of 350/mL (p < 0.05)." (PMID 36835202, 2023). "Given that IL-10 reduces Th2 cytokine secretion as well as eosinophilia in allergic mice, we further explored whether EV or NV could produce this anti-inflammatory cytokine on macrophages." (PMID 36604658, 2023). "The administration of IL-2 to healthy mice was effective at inhibiting eosinophilia in the lungs, which was associated with increased IL-10+ILC2 numbers, even in the absence of adaptive immune cells." (PMID 37947634, 2023).